BDNF (brain derived neurotrophic factor)
Diseases named in the same sentence as BDNF in open-access papers (continued):
Sharing a sentence is not in itself a finding about the gene and the disease.
neurodevelopmental disorder (62 papers, 2014 to 2026). A behavioral and cognitive disorder with onset during the developmental period that involves impaired or aberrant development of intellectual, motor, or social functions. "Impairments in BDNF signaling are associated with disrupted synaptic structure, memory deficits, and an increased risk for neurodevelopmental disorders." (PMID 40943255, 2025). "Interferences with BDNF signaling disrupt synaptic plasticity and ultimately circuit maturation and are implicated with neurodevelopmental disorders." (PMID 40362507, 2025). "Literature mining tools suggest regulation by BDNF and some relationship with genes implicated in neurodegeneration and neurodevelopmental disorders." (PMID 36261025, 2022). "BDNF‐induced accessible regions are linked to preferential exon usage by neurodevelopmental disorder‐related genes and the heritability of neuronal complex traits, which were validated in human iPSC‐derived neurons." (PMID 35996956, 2022). "BDNF is also increasingly implicated in the pathogenesis of neurodevelopmental disorders, particularly those found more frequently in males." (PMID 35354099, 2022). "Among the TFs corresponding to 276 different genes in the PFC, the brain-derived neurotrophic factor (BDNF) plays a key role in neurodevelopmental disorders and behavioral changes caused by general anesthesia." (PMID 35845920, 2022). "Based on our finding, M2 microglia-induced therapy in combination with BDNF can be a potential therapeutic strategy for the treatment of neurodevelopmental disorders caused by early life nicotine exposure." (PMID 34045967, 2021). "Given that reduced levels of full‐length Trio and the truncated mutations are linked to neurodevelopmental disorders and intellect0ual disability, our results highlight a potential connection between BDNF‐induced chromatin dynamics and exon‐specific gene expression in neuronal disorders." (PMID 35996956, 2022). "Given the role of aberrant synapse development in neurological dysfunction, our results herein suggest astrocyte BDNF/TrkB.T1 signaling may contribute to neurodevelopmental disorders in which BDNF signaling is implicated." (PMID 31433295, 2019). "This sex-specific association between cord serum BDNF and a parameter of attention at 12–14 months provides some support for the hypothesis that reduced serum BDNF levels at birth are linked to an increased risk for neurodevelopmental disorders." (PMID 35354099, 2022). "Consequently, these naturally lower levels of BDNF in boys early in life could render male infants at increased risk of neurodevelopmental disorders." (PMID 35354099, 2022). "Reduced BDNF levels can impair these processes, potentially leading to neurodevelopmental disorders like ADHD." (PMID 40700163, 2025). "In animal models, maternal infection alters BDNF and NGF expression in the fetal brain and maternal–fetal unit, potentially affecting synaptic development and increasing the risk of neurodevelopmental disorders." (PMID 40943255, 2025). "Neurotrophins, particularly BDNF and NGF, are key modulators of brain development and synaptic plasticity, and their dysregulation has been implicated in several neurodevelopmental disorders, including ASD, ADHD, ID, and tic disorders." (PMID 40943255, 2025). "We analyzed BDNF as a marker for injury because fetal brain injuries and other neurodevelopmental disorders often are accompanied by changes in BDNF expression." (PMID 36613580, 2022). "Brain derived neurotrophic factor (BDNF) plays key roles in several neurodevelopmental disorders and actions of pharmacological treatments." (PMID 25414642, 2014). "A consensus of the role of BDNF in neurodevelopmental disorders is related to its role in the regulation of synaptic maturation within critical brain areas." (PMID 25414642, 2014).
neurodevelopmental disorder (continued). "Additionally, a decrease in the mRNA levels of BDNF, cAMP-responsive element, and stem cell factor were observed, which are an important modulators of neuroplasticity, thus leading to neurodevelopmental disorders." (PMID 40063073, 2025). "Because brain development depends on BDNF function, it is not surprising that BDNF impairment is implicated in some of the psychopathology observed in different neurodevelopmental disorders." (PMID 39194714, 2024). "In conclusion, SPRY2 is an effective regulatory protein of the FGF/VEGF/EGF/BDNF signaling pathway and could be targeted as a therapeutic molecule in neurodevelopmental disorders." (PMID 39456824, 2024). "Finally, we recapitulate the effects of BDNF signaling disruption in GABAergic neurons and its relationship with neurodevelopmental disorders." (PMID 39125882, 2024). "For example, the regulation of NKCC1 and KCC2 function by BDNF–TrkB signaling during neuronal development has been widely accepted, and re‐establishing E/I homeostasis provided therapeutic potential against neurodevelopmental disorders." (PMID 37545014, 2023). "At birth, male infants naturally have significantly lower serum BDNF levels (∼10–20% lower than females), which may render them more vulnerable to neurodevelopmental disorders." (PMID 35354099, 2022). "Reduced serum BDNF concentrations were recently described in patients with neurodevelopmental disorders or neurodegenerative diseases (Alzheimer, Parkinson, and Huntington’s), suggesting a possible role for this neurotrophin as an effect biomarker in these diseases." (PMID 36710936, 2022). "Similarly, DNA methylomic alterations are also linked to BDNF and HPA axis deficits in neurodevelopmental disorders as well as in DNE children and animal models." (PMID 32138755, 2020). "Since the direction of the BDNF changes was unexpected, this study emphasizes the need for further exploration of BDNF and related molecules as biomarkers of response to treatment in neurodevelopmental disorders including FXS." (PMID 28616097, 2017). "In addition, several studies suggested that a decreased of BDNF activity may be involved in ethanol-induced neurodegeneration and in the etiology of ethanol-related neurodevelopmental disorders." (PMID 32660138, 2020). "Numerous studies involving animals have shown that polyphenols sourced from plants can markedly increase the levels of brain-derived neurotrophic factor (BDNF), leading to improvements in neurodevelopmental disorders." (PMID 40612741, 2025). "Among other RTKs, Trk receptor-BDNF mediated and FGF-mediated signaling have been the most studied in nervous system development and neurodevelopmental disorders." (PMID 39456824, 2024). "Of particular relevance is recent work in one of the most clinically relevant mouse models of Rett syndrome, a neurodevelopmental disorder that shares many neurobiological features with FXS, including abnormal BDNF signaling." (PMID 34433831, 2021). "Furthermore, low levels of BDNF have been reported in newborns who later developed ASD, suggesting its potential as a biomarker for neurodevelopmental disorders." (PMID 37469977, 2023). "In this context, to our knowledge, this is the first study demonstrating the involvement of structural variation of the BDNF gene in the pathogenesis of BDs in the absence of a neurodevelopmental disorder." (PMID 31769621, 2020). "Although RBM4 is not yet known to be linked to any neurodevelopmental disorders, our result that chronic treatment with 7,8-DHF improved motor learning in young Rbm4dKO adults provides a means to correct behavioral abnormalities associated with BDNF deficiency." (PMID 37670183, 2023). "Therefore, we could not compare the absolute peripheral BDNF level of patients with ADHD or other DSM-5 neurodevelopmental disorders." (PMID 27200107, 2016).
metabolic disorders (60 papers, 2010 to 2025). "Physical inactivity increases the risk of metabolic diseases as it leads to the release of specific muscle-derived cytokines, such as myonectin, irisin, brain-derived neurotrophic factor (BDNF), and decorin." (PMID 38136166, 2023). "Recent studies reported the relationships between circulating BDNF and metabolic disorders, which is closely associated with brain function." (PMID 33375318, 2020). "In this regard, alterations in the level of BDNF expression and secretion, due to polymorphisms, could be linked to the development and/or progression of neurodegenerative and metabolic disorders." (PMID 33269104, 2020). "Interestingly, both SH2B1 and BDNF are obvious candidate genes for metabolic disorders based on the biological roles of the encoded proteins." (PMID 21912638, 2011). "Moreover, although there have been fewer studies exploring the relationship between BDNF and metabolic disorders, there is evidence of an association between BDNF and the reduction in BMI, waist circumference, glucose, insulin, and risk for T2DM, mainly in Asian populations." (PMID 38997780, 2024). "In metabolic disorders, BDNF expression exhibits vulnerability to chronic stress and disease progression." (PMID 41305665, 2025). "The potential mechanisms involve the restoration of metabolic disorders in the tryptophan pathway and BDNF depletion." (PMID 40672547, 2025). "Decreased serum levels of adropin and BDNF have been also reported in people with metabolic disorders such as obesity, diabetes mellitus, and CVDs9–11." (PMID 37777675, 2023). "Future research should include larger samples and more sophisticated design in pediatric and adolescent populations to elaborate on the physiology of BDNF regarding metabolic disorders." (PMID 37548699, 2023). "Some previous studies have investigated the relationship between dietary intakes and metabolic disorders with BDNF and adropin." (PMID 37996610, 2023). "Recent studies highlighted that circulating brain-derived neurotrophic factor (BDNF) in the bloodstream is correlated with metabolic disorders and that metabolic disorders were suggested to have a strongly positive relationship with brain function." (PMID 33375318, 2020). "Several additional factors can however influence the basal synthesis of BDNF at the individual level such as genetic variation, metabolic disorders, and/or inflammatory process and hence the BDNF response to aerobic-type training." (PMID 31921371, 2020). "The non-coding RNAs are assuming escalating importance in the regulation of metabolic disease at RNA levels, linking nutritional influence, neuroinflammation and brain-derived neurotrophic factor (BDNF) pathway." (PMID 31798417, 2019). "Recently, impairment of BDNF-related intracellular signaling in metabolic diseases has been demonstrated." (PMID 25309465, 2014). "Furthermore, dietary intake of omega-3 (n-3) PUFAs has been positively associated with serum BDNF concentrations in adolescents, suggesting a potential link between PUFA intake and neurotrophic support in the context of psychiatric and metabolic disorders." (PMID 41305665, 2025). "These metabolic disorders may influence BDNF biosynthesis and secretion through multiple mechanisms." (PMID 40933306, 2025). "Further supporting this hypothesis, prior studies have shown divergent trends in circulating BDNF levels in metabolic diseases." (PMID 40791659, 2025). "Additionally, elderly individuals with T2DM often face metabolic disorders that impede BDNF synthesis and further reduce BDNF levels." (PMID 40933306, 2025). "Recent studies have also highlightedits involvement in the regulation of glucose and energy metabolism, suggestingthat BDNF may contribute to metabolic disorders, including those induced byantipsychotic medications like clozapine." (PMID 41523972, 2025).
metabolic disorders (continued). "Indeed, IPA identified pathways and gene interaction networks involved in increased heart apoptosis, activation of cardiac inflammation and ROS, and increased body weight and metabolic disorders in MYH6-Cre-BDNF–/– hearts." (PMID 36061561, 2022). "It remains unclear to what extent DA metabolic disorders and reduced BDNF expression are interrelated." (PMID 36498900, 2022). "We were also unable to adjust for other variables that may explain additional variance in serum BDNF levels, such as physical activity, diet, metabolic diseases, smoking and other substance use, social engagement, and stress." (PMID 34408648, 2021). "The identification of circuitry which integrates signals from food intake and energy expenditure and the elucidation of the mechanisms by which BDNF acts on them will lay the groundwork in building a healthy and balanced life and deepening the comprehension of human metabolic diseases." (PMID 34833132, 2021). "BDNF can have protective function against cardiovascular and metabolic disorders." (PMID 33343231, 2020). "Both BDNF and SH2B1 have been implicated in metabolic diseases." (PMID 24260264, 2013). "Moreover, the relationship between BDNF and metabolic disorders cannot be ignored, taking into consideration the assumptions of the hypothesis of metabotropic deficit mentioned in the introduction." (PMID 35769087, 2022). "In addition, a better understanding of the role of this endogenous peptide in health and disease may pave the way to exploit BDNF as a novel therapeutic agent for neurodegenerative and metabolic diseases such as T2D." (PMID 34215825, 2021). "In this paper, the molecular dynamics including downregulation of BDNF in brain tissues and altered activity of the HPA axis in PPD, inflammatory conditions, and metabolic disease are discussed." (PMID 25309465, 2014). "A skeletal muscle contraction-induced derivative protein, BDNF can increase fat oxidation in skeletal muscle through the AMPK pathway and may be a possible therapy for metabolic diseases." (PMID 39309455, 2024). "Considering the role of visceral fat in metabolic disorders and the involvement of BDNF in metabolic health status, identification and management of HTGW and low serum BDNF values are crucial steps in preventing and decreasing the incidence rate of these disorders." (PMID 36185667, 2022). "Like BDNF, GDNF seems to have a role in the suggested metabotropic hypothesis of metabolic disorders." (PMID 34512552, 2021). "After 5 weeks of Gas administration, neuroprotective effects were observed, metabolic disorders were alleviated, and hippocampal ERS could be reduced to improve BDNF expression in DM rats." (PMID 30524286, 2018). "Furthermore, brain-derived neurotrophic factor (BDNF) promotes lipid oxidation through AMPK activation within skeletal muscle, contributing to improved energy metabolism efficiency, enhanced endurance, and prevention of metabolic diseases." (PMID 41149619, 2025). "It is also important to consider that BDNF and TrkB might not be optimal targets for intervention strategies for metabolic disorders, as they are broadly expressed in the brain and play a multitude of functions." (PMID 38672441, 2024).
central nervous system disorder (18 papers, 2013 to 2025). A disease involving the central nervous system. "Several disorders of the central nervous system are associated with a reduction in the circulating level of BDNF and genetic alteration of BDNF." (PMID 32679912, 2020). "A certain central nervous system disorder pathomechanism may be associated with the dysfunction of the BDNF/TrkB system." (PMID 33343231, 2020). "Extensive studies have been undertaken to investigate the relationship between low BDNF levels and central nervous system disorders." (PMID 38001940, 2023). "Brain-derived neurotrophic factor (BDNF), a member of the neurotrophin family, is involved in neural development and plays a protective role in central nervous system disorders." (PMID 30424498, 2018). "We also examined BDNF/TrkB/p75NTR signal because BDNF/TrkB performs a neuroprotective role in various central nervous system diseases." (PMID 28359334, 2017). "Research has shown that BDNF is crucial in the treatment of central nervous system diseases." (PMID 38783169, 2024). "There are several up-regulated genes within the hippocampus, such as BDNF, NPY2R, and Gria1, and downregulated genes such as Arc, which are well known in the neural plasticity and pathogenesis of central nervous disease and abnormal behavior." (PMID 34045967, 2021). "Additionally, BDNF induces a rapid increase in the total number of cell surface GABA(A) receptors by activating Trk B receptors, suggesting a relationship between GABA(A) receptor deficits and central nervous system disorders." (PMID 40002459, 2025).
peripheral neuropathy (17 papers, 2012 to 2026). A disorder affecting the peripheral nervous system. "Many biomarkers are being studied currently, including TNF-like weak inducer of apoptosis (TWEAK), lipocalin 2 (LCN2, an iron transporter in innate immunity), S100B (strongly associated with peripheral neuropathy), and brain-derived neurotrophic factor (BDNF)." (PMID 38893713, 2024). "Peripheral neuropathy is linked to low levels of BDNF, highlighting its role in maintaining the health of sensory neurons in the peripheral nervous system." (PMID 39568824, 2024). "NGF, BDNF and NT-3 deficiencies have been correlated with severe peripheral neuropathy and death of the organism." (PMID 24312363, 2013). "Therefore, the grade of BDNF protein may be a tool for Chemical-induced peripheral neuropathy risk assessment." (PMID 35710565, 2022). "By using an adipocyte-tropic adeno-associated virus (AAV) to deliver BDNF or NGF to subcutaneous white adipose tissue, the effects of BDNF and NGF on adipose tissue in combination to peripheral neuropathy was examined." (PMID 39194496, 2024). "HuD-dependent GAP–43 and BDNF increase has been shown in the DRG and axons during nerve regeneration in peripheral neuropathy models and growing evidence associates mRNAs HuD target to neurological and neurodegenerative disorders." (PMID 36696009, 2023). "We aimed to evaluate the potential of serum neurofilament light chain (sNfL) and serum brain-derived neurotrophic factor (sBDNF) as reliable biomarkers for paclitaxel-induced peripheral neuropathy (PIPN)." (PMID 36059704, 2022). "BDNF in the spinal dorsal horn contributes to the development of NRTI-induced painful peripheral neuropathy." (PMID 24403874, 2013). "BDNF may be involved in the development of chemotherapy-induced peripheral neuropathy (CIPN), and its blood concentration is inversely correlated with the severity of bortezomib-induced neuropathy." (PMID 36059704, 2022).